ARSA (arylsulfatase A)
Diseases named in the same sentence as ARSA in open-access papers (continued):
Sharing a sentence is not in itself a finding about the gene and the disease.
metachromatic leukodystrophy (continued). "In the ARSA−/− mouse model of metachromatic leukodystrophy (MLD), treatment with AAV-ARSA gene therapy significantly elevates ARSA enzymatic activity in the brain and reduces systemic sulfatide accumulation." (PMID 41155400, 2025). "Metachromatic leukodystrophy (MLD; OMIM 250100) is an inherited autosomal recessive lysosomal storage disease (LSD), usually caused by variants in the arylsulfatase A gene (ARSA), which encodes the enzyme arylsulfatase A (ASA)." (PMID 38383398, 2024). "Metachromatic Leukodystrophy (MLD) is a fatal demyelinating lysosomal storage disease with no approved treatment; it is caused by mutation in arylsulfatase A (ARSA) gene that results in accumulation of sulphatides in neural and glial cells." (PMID 29379168, 2018). "In family 023, the proband exhibits low activity of arylsulfatase A (ARSA), leading to metachromatic leukodystrophy (MIM#250100)." (PMID 27435318, 2016). "Metachromatic leukodystrophy disorder (MLD) is one of the rare neurometabolic diseases caused due to lack of saposin B and arylsulfatase A enzyme deficiency." (PMID 26401154, 2015). "NBS for metachromatic leukodystrophy (MLD) by measurement of the arylsulfatase A activity in DBS is almost certainly not feasible because of the enormous pseudodeficiency problem." (PMID 30882045, 2018). "Recently, genetically modified HSCT, termed HSCGT (Hematopoietic Stem Cell - Gene Therapy) has been used successfully to treat metachromatic leukodystrophy patients (MLD) who re-introduced the patients’ own CD34+cells with lentivirus-transfected cells, overexpressing arylsulfatase A (ARSA)." (PMID 32351971, 2020).
lysosomal storage disease (54 papers, 2006 to 2025). A metabolic disorder caused by mutations in proteins critical for lysosomal function, including lysosomal enzymes, lysosomal integral membrane proteins, and proteins involved in the post-translational modification and trafficking of lysosomal proteins. "Metachromatic leukodystrophy (MLD) is an autosomal recessive lysosomal storage disorder that presents in patients who have a deficiency in arylsulfatase A (ARSA) activity." (PMID 39276676, 2024). "Metachromatic leukodystrophy (MLD) is an ultra-rare and fatal inherited lysosomal storage disease caused by a deficiency of arylsulfatase-A (ARSA), due to mutations in the ARSA gene." (PMID 39051401, 2024). "MLD is a lysosomal storage disease leading to sulfatide accumulation due to a deficiency of the lysosomal enzyme ARSA, causing clinical manifestations characterized by progressive motor and cognitive deficits." (PMID 35857900, 2022). "Metachromatic leucodystrophy (MLD) is a rare inherited lysosomal disorder caused by reduced activity of the enzyme arylsulfatase A with accumulation of sulfatides in the nervous system." (PMID 30197627, 2018). "MLD is a kind of lysosomal storage disorder due to the deficiency of the ARSA enzyme, which is involved in the metabolism of membrane sulfatides into galactosylceramide." (PMID 30057904, 2018). "In conclusion, MLD and other lysosomal disorders are considered to be orphan diseases but the expected incidence of fetuses conceived with two pathogenic ARSA mutations of 4.1 in 100 000 and heterozygote frequency of 1 in 79 negate this statement." (PMID 21695197, 2011). "Mutations in the ARSA gene often cause autosomal recessive lysosomal storage disorder." (PMID 35486332, 2022). "ARSA mutations, similar to GBA mutations, have been previously linked to lysosomal storage diseases (LSDs)." (PMID 32019516, 2020). "In arylsulfatase A KO mice, sulfogalactosylglycerolipid, a major sulfoglycolipid of male germ cells, accumulated in Sertoli cells at 8 months with buildup seen as lysosomal swelling and other cellular abnormalities typical of a lysosomal storage disorder." (PMID 37756356, 2023). "HSPC-LVGT expressing arylsulfatase A (ARSA) has been shown to improve CNS pathology for MLD, another lysosomal storage disease." (PMID 36284764, 2022).
Krabbe disease (9 papers, 2012 to 2024). A lysosomal disorder that affects the white matter of the central and peripheral nervous systems. "Krabbe disease and MLD are caused by deficiencies in the lysosomal enzymes galactosylceramidase (GALC) and arylsulfatase A (ARSA), respectively." (PMID 34262084, 2021).
leukodystrophy (8 papers, 2015 to 2023). Leukodystrophies are a group of rare, progressive, metabolic, genetic diseases that affect the brain, spinal cord and often the peripheral nerves. "MLD, which results from a deficiency of the lysosomal enzyme arylsulfatase A (ARSA), is a leukodystrophy which exhibits neurological damage with similar phenotypes to that of CD, such as ataxia and seizures, in addition to early infantile or juvenile death." (PMID 33967698, 2021). "The diagnosis should be suspected in individuals with progressive neurologic dysfunction, MRI evidence of leukodystrophy, or low arylsulfatase A activity in leukocytes." (PMID 37761400, 2023). "Leukodystrophies are genetic disorders of the CNS leading to progressive neurologic deterioration; in the case of MLD, the disease arises from a deficiency of the lysosomal enzyme arylsulfatase A (ARSA) due to LoF mutations in the ARSA gene." (PMID 34690692, 2021). "In leukodystrophy pseudo-deficiency, a mutation in the predominate yet rare AATAAC proximal PAS of arylsulfatase A (ARSA) to AGTAAC results in increased use of distal canonical PASs and reduced expression, potentially through the lengthened 3′ UTR allowing miRNA- or RBP-mediated silencing." (PMID 32560344, 2020).
demyelinating disease (5 papers, 2011 to 2025). A broad group of disorders that affect the myelin sheaths that cover the neurons. "This is a devastating demyelinating disease caused by a deficiency of the enzyme sulfatide sulfatase, also known as arylsulfatase A (ASA)." (PMID 22937274, 2011). "In addition, because MLD is a demyelination disease, we assessed ARSA protein expression in myelin-forming cells." (PMID 34654893, 2021).
sphingolipidosis (5 papers, 2022 to 2023). An inherited metabolic disorder that affects the lysosomal degradation of the spinhgolipids. "Rare variants in genes causing sphingolipidosis (ARSA (rs201251634) and HGSNAT (rs766835582)) and mucopolysaccharidosis (IDUA (rs532731688, rs74385837) were revealed in SCZ patients but not in controls." (PMID 38248833, 2023). "MLD is a sphingolipidosis caused by lysosomal enzyme arylsulfatase A (ARSA) deficiency or its sphingolipid activator protein B (SapB)." (PMID 36848337, 2023). "In the sphingolipidosis MLD, deficiency of the aryl-sulfatase A (ARSA) enzyme leads to accumulation of sulfatides, including multiple sulfated glycolipids." (PMID 39697359, 2022).
Cognitive impairment (4 papers, 2020 to 2023). Abnormal cognition is characterized by deficits in thinking, reasoning, or remembering. "Based on the type of mutation and degree of arylsulfatase A enzyme (ARSA) deficiency, MLD can show a wide spectrum of clinical manifestations that range from cognitive impairment to progressive abnormalities of motor and language function and early death." (PMID 33923989, 2021). "Moreover, proteins associated with cognitive impairments, like GRN, ARSA, NCAM1, and GUSB, also showed marked differences in protein levels." (PMID 32850779, 2020).
cognitive decline (3 papers, 2021 to 2025).
autism (2 papers, 2009 to 2023). Persistent deficits in social interaction and communication and interaction as well as a markedly restricted repertoire of activity and interest as well as repetitive patterns of behavior. "Inspection of the remaining genes in the non-complex-autism group CNVs revealed three additional genes functioning in the same processes (B4GALT1, ARSA, and GALNTL5), for which Prioritizer had determined borderline significance (0.057<nominal p-value<0.074)." (PMID 19492091, 2009).
lung carcinoma (2 papers, 2014 to 2021). "However, as the authors refer, there are some cases of cancer cells where arylsulfatases (ARS) are overexpressed (ARSA and ARSB), as in human lung cancer, pertaining to one of the cell lines tested that yielded lower toxicity of extracts, comparatively to fibroblasts." (PMID 33445445, 2021).
diabetes (1 paper, 2023). "LPC is independently associated with diabetes, and hepatic arylsulfatase A increased LPC and LPA in lipid rafts, which improved muscle insulin sensitivity." (PMID 37669305, 2023).
diabetic nephropathy (1 paper, 2020). "Two lysosomal enzymes, ARSA and GLB1, were highlighted as part of the predictive profile for diabetic nephropathy." (PMID 32453760, 2020).
essential tremor (1 paper, 2020). A relatively common disorder characterized by a fairly specific pattern of tremors which are most prominent in the upper extremities and neck, inducing titubations of the head. "The potential role of ARSA gene mutations in PD has been illustrated in a recent study that genetically analyzed a female patient of Japanese descent with adult-onset MLD and a positive family history of PD with mild cognitive dysfunction and probable essential tremor." (PMID 33036336, 2020).
generalized dystonia (1 paper, 2022). "In eight patients with generalized dystonia from infancy, the mutation of PIGA, TCF4, CHRNG, SLC16A2, KCNQ2, NACC1, CTNNB1, or ARSA gene were found to be causative." (PMID 35719373, 2022).
Hearing impairment (1 paper, 2025). A decreased magnitude of the sensory perception of sound. "Treatment with AAV.GMU01-ARSA restored ARSA activity to WT levels in various tissues, normalizing sulfatide levels, reducing neuroinflammatory markers, and reversing hearing impairment." (PMID 40536808, 2025).
ichthyosis (1 paper, 2021). Disorders of cornification that are characterized by visible scaling and/or hyperkeratosis of most or all of the skin. "While ARSA deficiency seems a cause for neurological symptoms and later neurodegenerative disease course, deficiency of other sulfatases results in clinical features such as dysmorphism, dysostosis, or ichthyosis." (PMID 33728250, 2021).
Insulin resistance (1 paper, 2022). Increased resistance towards insulin, that is, diminished effectiveness of insulin in reducing blood glucose levels. "We reveal striking hepatokine remodelling that is associated with insulin resistance and maladaptive lipid metabolism, and identify arylsulfatase A (ARSA) as a hepatokine that is upregulated in NASH and type 2 diabetes." (PMID 35273160, 2022).
keloid (1 paper, 2023). An irregularly shaped, elevated mark on the skin caused by deposits of excessive amounts of collagen during wound healing. "We explored the potential role of GSL metabolism pathway in keloid, classfied keloids based on GSLMRGs expression patterns, provided a set of gene markers including GLTP, GALC, ARSA, HEXB, SUMF2, and GBA2, and constructed a diagnostic model for keloid." (PMID 37168863, 2023). "A strong correlation between IL-7 and GLTP, GALC, ARSA, HEXB, and SUMF2 was found, suggesting that IL-7-based inflammatory factors may involve in keloid growth and development through associating with the GSL metabolism pathway." (PMID 37168863, 2023). "In this study, the differential GSLMRGs of keloid and the top ten genes with the highest importance from machine learning algorithms Random Forest and SVM-RFE were intersected, and six candidate GSLMRGs were identified: ARSA, GBA2, SUMF2, GLTP, GALC, and HEXB." (PMID 37168863, 2023).
liposarcoma (1 paper, 2007). A usually painless malignant tumor that arises from adipose tissue. "In addition, genes involved in receptor activity, signaling and lipid metabolism (some of which have previously been reported in liposarcoma) such as ACAA2, ARSA, DHRS3, PDE3A, and PPARA, were upregulated." (PMID 17359542, 2007).
melanoma (1 paper, 2018). A malignant, usually aggressive tumor composed of atypical, neoplastic melanocytes. "According to Pubmed searches, ARSA, the arylsulfatase A gene, appears to mediate BAG1, PEX3, and WIPI1 interaction with melanoma." (PMID 30622661, 2018). "Interestingly, ARSA (arylsulfatase A) is the only ARG mediating BAG1, PEX3, and WIPI1 relation with melanoma." (PMID 30622661, 2018).
meningioma (1 paper, 2020). A generally slow growing tumor attached to the dura mater. "Proteins involved in neutrophil degranulation, such as ARSA, GCA, FUCA1, PRTN3, ELANE, MNDA, and LCN2, were identified uniquely or with differential abundance in male meningiomas." (PMID 32587372, 2020).
Obesity (1 paper, 2011). Accumulation of substantial excess body fat. "Whether obesity is associated with alterations in ARSA activity, DAR expression, and/or changes in the signaling pathways that are activated by DA, is an intriguing issue which deserves further exploration." (PMID 21966540, 2011).
pervasive developmental disorder (1 paper, 2015). A category of developmental disorders characterized by impaired communication and socialization skills. "Although a slight deficiency in ARSA activity, with levels 50–70 % that of controls, might be associated with pervasive developmental disorders, ARSA pseudodeficiency does not lead to neurological impairments." (PMID 26553228, 2015).
Sensorimotor neuropathy (1 paper, 2015). "Our diagnosis was confirmed by EMG-NCV findings with sensorimotor neuropathy pattern and the assessment of arylsulfatase A enzyme function." (PMID 26401154, 2015). "Sensorimotor neuropathy pattern and brain imaging findings in our patients lead us to check the arylsulfatase A enzyme function." (PMID 26401154, 2015).
steatosis (1 paper, 2022). Increased lipid within the cytoplasm of cells. "ARSA mRNA expression tended to increase with NAFL and was strongly upregulated with NASH, effects that were related to steatosis and hepatocyte ballooning, but not inflammation or fibrosis." (PMID 35273160, 2022).
type 2 diabetes (1 paper, 2022). "Together, this study provides a unique resource describing global changes in hepatokine secretion in NASH, and identifies ARSA as a regulator of liver to muscle communication and as a potential therapeutic target for type 2 diabetes." (PMID 35273160, 2022). "Using this system, ARSA was identified as a liver-secreted protein that is increased in NAFLD/NASH and type 2 diabetes in humans." (PMID 35273160, 2022).
velocardiofacial syndrome (1 paper, 2007). "For this reason, fluorescent in situ hybridization was performed using DNA fluorescent probes for the DiGeorge/velocardiofacial syndrome critical region (TUPLE1) at 22q11.2 and a control probe, arylsulfatase-A (ARSA), at 22q13.3, from a commercially available source (Vysis)." (PMID 18053182, 2007).
neurodegenerative disease (7 papers, 2014 to 2025). A disorder of the central nervous system characterized by gradual and progressive loss of neural tissue and neurologic function.
cancer (5 papers, 2019 to 2026). A tumor composed of atypical neoplastic, often pleomorphic cells that invade other tissues. "Many peripheral organs, including several cancers, produce arylsulfatase A (ARSA), a secretable lysosomal enzyme that can de-conjugate DA-S and convert it into bioactive DA." (PMID 35582277, 2019). "Pathogenic or likely pathogenic variants in cancer-associated genes were identified in 37 (6.8%), most frequently in MITF, DICER1, and BRCA2, while 43 (7.9%) harbored variants in NDD-related genes, including DHCR7, POLG, and ARSA." (PMID 41844650, 2026). "It probably interacts with the Wnt and ARSA/ARSB pathways and is involved in the process of EMT of carcinoma cells." (PMID 31205468, 2019).
metabolic disease (3 papers, 2015 to 2022). A congenital disorder (due to inherited enzyme abnormality) or acquired (due to failure of a metabolically important organ) disorder resulting from an abnormal metabolic process. "ARSA was overexpressed in the livers of obese db/db mice using adeno-associated virus (ARSA-AAV) to recapitulate a state of metabolic disease." (PMID 35273160, 2022). "MLD is an inheritance metabolic disorder, which was confirmed by the assessment of arylsulfatase A enzyme function, peripheral blood leukocyte that assessed in a referral laboratory in Iran." (PMID 26401154, 2015).
peripheral neuropathy (2 papers, 2019 to 2025). A disorder affecting the peripheral nervous system. "Since ARSA knockout mouse models do not show clear demyelination or peripheral neuropathy, the use of double-transgenic mASA2/2 mice is recommended to study inflammation and treatment effects on the PNS." (PMID 31684987, 2019).
brain disease (1 paper, 2021). "Because MLD is a whole brain disease, this limited ARSA expression may not be sufficient to eliminate the MLD disease phenotype." (PMID 34654893, 2021).
movement disorder (1 paper, 2020). Neurological conditions resulting in abnormal voluntary or involuntary movement, which may impact the speed, fluency, quality and ease of movement. "Notably, a positive family history for movement disorders was mainly reported in the subgroup of patients with atypical symptoms, highlighting the potential contribution of ARSA gene polymorphisms or other inheritable factors affecting ASA activity in this clinical variability." (PMID 33036336, 2020).
neurological disease (1 paper, 2022). "Sporadic case reports associating ARSA deficiency with otherwise unexplained neurological disorders must be interpreted with caution, as hereditary disorders were broadly underdiagnosed before the introduction of next‐generation sequencing (NGS) techniques into routine diagnostics." (PMID 35822086, 2022).
psychiatric disorder (1 paper, 2023). A disorder characterized by behavioral and/or psychological abnormalities, often accompanied by physical symptoms. "We identified three male-specific genes (ARSA, IGF1R, and SNX19) and two female-specific genes (LEMD2 and PCP4) in psychiatric disorders." (PMID 37794117, 2023).
ARSA also shares sentences with these, for which no sentence is quoted: Ataxia (4 papers); epilepsy (4); Parkinson disease (4); autosomal recessive disease (3); dementia (3); (ARSA) deficiency (2); genetic disorder (2); infertile (2); mucopolysaccharidosis I (2); Parkinsonism (2); schizophrenia (2); adrenoleukodystrophy (1); Adult onset (1); Alzheimer disease (1); astrocytoma (1); cardiac hypertrophy (1); cerebellar ataxia (1); Cerebroretinal vasculopathy (1); COVID-19 (1); cranial neuropathy (1); Dyskinesia (1); dysostosis (1); Dystonia (1); Farber’s disease (1); Gaucher disease (1); GM1 gangliosidosis (1); Leukoencephalopathy (1); Lewy body disease (1); Lysosomal disease (1); male infertility (1).
A further 20 diseases each share a sentence with ARSA in 1 paper.